MYORG (myogenesis regulating glycosidase)
Description:
Alpha-galactosidase with unusual specificity for the Gal-alpha1,4-Glc structure, whose in vivo substrate is still unknown. Promotes myogenesis by activating AKT signaling through the maturation and secretion of IGF2 (By similarity).
Synonyms: KIAA1161; NET37; IBGC7
Tractability: Small molecule: a structure with a bound ligand is known. Antibody: UniProt predicts a signal peptide or a membrane-spanning region. PROTAC: ubiquitination databases record sites on it.
Gene: Protein-coding gene on chromosome 9 (34,366,666 to 34,377,150, reverse strand). Ensembl gene ENSG00000164976.
Subcellular location: Nucleus membrane; Endoplasmic reticulum membrane
Subcellular location (Human Protein Atlas): Mitochondria
Gene Ontology:
Molecular function: alpha-galactosidase activity; hydrolase activity, hydrolyzing O-glycosyl compounds
Biological process: skeletal muscle fiber development; positive regulation of insulin-like growth factor receptor signaling pathway; positive regulation of phosphatidylinositol 3-kinase/protein kinase B signal transduction; carbohydrate metabolic process
Cellular component: endoplasmic reticulum membrane; nuclear membrane
Genetic constraint (gnomAD): Loss-of-function variants: 45 observed, 47.83 expected, observed/expected ratio (o/e) 0.94, 90% interval 0.74 to 1.21. The upper end of that interval is the gene's LOEUF score, 1.21, which puts it in group 5 of 6, group 1 being the genes least tolerant of losing a copy. Missense variants: 1,110 observed, 1,045.2 expected, observed/expected ratio (o/e) 1.06, 90% interval 1.01 to 1.12. Synonymous variants: 552 observed, 467.92 expected, observed/expected ratio (o/e) 1.18, 90% interval 1.1 to 1.27.
Homologues: Orthologues: chimpanzee MYORG (99% identical), macaque MYORG (98% identical), dog MYORG (94% identical), rabbit MYORG (93% identical), pig MYORG (93% identical), rat Myorg (92% identical), mouse Myorg (92% identical), tropical clawed frog myorg (68% identical), zebrafish myorg (64% identical), zebrafish MYORG (59% identical), Drosophila melanogaster tobi (30% identical), Caenorhabditis elegans aagr-4 (15% identical), and 2 more. Paralogues in human: GAA (19% identical), MGAM (19% identical), MGAM2 (18% identical), SI (18% identical), GANAB (17% identical), GANC (16% identical).
Diseases named in the same sentence as MYORG in open-access papers:
MYORG is named in the same sentence as 21 diseases in open-access papers, as found by Europe PMC text mining. Sharing a sentence is not in itself a finding about the gene and the disease. The quoted sentences say what the papers report.
cognitive decline (4 papers, 2020 to 2025). "Dysarthria (even isolated) is almost universally present in symptomatic MYORG-mutation carriers that tend to display a phenotype dominated by progressive cerebellar signs with ataxia and cognitive decline." (PMID 36862146, 2023). "The mutation of MYORG has led to primary familial brain calcification, wherein various brain regions exhibited abnormal calcium depositions linked to psychiatric conditions, motor impairments, and cognitive decline." (PMID 40332944, 2025). "MYORG patients and subjects with cognitive decline tended to have higher scores and bladder involvement compared to other groups." (PMID 38999439, 2024). "MYORG patients can also show a phenotype similar to progressive supranuclear palsy (PSP) with vertical gaze palsy, progressive cognitive decline and early falls in the context of akinetic-rigid parkinsonism." (PMID 36862146, 2023). "Significantly higher bladder sub-scores were found in MYORG patients (compared to SLC20A2 subjects and patients without known genetic variants, p = 0.009), as well as in subjects with parkinsonism and cognitive decline compared to asymptomatic subjects (p = 0.042)." (PMID 38999439, 2024).
Fahr's disease (4 papers, 2021 to 2025). "Next, the homozygous, pathogenic variant in the MYORG gene leads to the diagnosis of Fahr’s disease." (PMID 41465080, 2025). "A set of causative genes associated with primary familial brain calcification (PFBC) has now been identified, and include genes such as SLC20A2, PDGFB, PDGFRB, XPR1, MYORG, and JAM2." (PMID 37240341, 2023). "Genes implicated in Fahr's disease include PDGFB, PDGFRB, SLC20A2, XPR1, MYORG, and JAM2." (PMID 37780723, 2023).
Parkinsonism (4 papers, 2020 to 2025). Characteristic neurologic anomaly resulting from degeneration of dopamine-generating cells in the substantia nigra, a region of the midbrain, characterized clinically by shaking, rigidity, slowness of movement and difficulty with walking and gait. "Parkinsonism with vertical nuclear gaze palsy was uncommon in MYORG mutation carriers, but occurred in case 4, thus, extending the phenotypic spectrum of MYORG-related PFBC." (PMID 34745211, 2021). "Patients with MYORG variants tend to display a homogeneous clinical spectrum, showing extensive brain calcification and parkinsonism, dysarthria, ataxia, or vertigo." (PMID 34745211, 2021). "Patients with MYORG mutations tend to display a homogeneous clinical spectrum, showing dysarthria, parkinsonism, gait disorder, and ataxia." (PMID 34745211, 2021). "Urinary symptoms were also reported in more than 1/3 of the cohort, with higher rates in MYORG patients and in those with parkinsonism and cognitive impairment." (PMID 38999439, 2024). "Notably, other related genes, such as “PDGFRB,” “MYORG,” “XPR1,” and “JAM2,” as well as phenotypic traits like “dementia” and “parkinsonism,” also exhibited significant node sizes." (PMID 40456615, 2025).
Ataxia (3 papers, 2020 to 2024). Ataxia refers to impaired coordination of voluntary muscle movement. "Dysarthria was a relevant clinical finding in 28% of the cohort, reaching a 75% frequency in MYORG mutation carriers (p = 0.04), who also had higher rates of ataxia (62.5%) compared to other sub-groups." (PMID 38999439, 2024).
Dysarthria (3 papers, 2021 to 2025). Dysarthric speech is a general description referring to a neurological speech disorder characterized by poor articulation. "As reported, dysarthria was shown to be a common prominent feature in the majority of symptomatic cases with MYORG mutations compared with those with mutations in the dominant-causing genes." (PMID 34745211, 2021). "Secondly, certain outcomes were based on a limited number of studies, such as those reporting MYORG variant detection rates and the prevalence of dysarthria phenotypes, which were derived from only three studies, potentially compromising the accuracy of the results." (PMID 40456615, 2025). "Even within the limits of our sample size, MYORG patients confirmed their distinctive and more severe phenotype, featuring dysarthria and cognitive involvement, as previously reported." (PMID 38999439, 2024). "MYORG patients also had prominent language difficulties in addition to dysarthria." (PMID 38999439, 2024).
Cerebellar atrophy (2 papers, 2021 to 2023). Cerebellar atrophy is defined as a cerebellum with initially normal structures, in a posterior fossa with normal size, which displays enlarged fissures (interfolial spaces) in comparison to the foliae secondary to loss of tissue. "Radiological patterns of calcium deposition are similar in all known genetic forms, but central pontine calcification and cerebellar atrophy are highly suggestive of MYORG mutations and extensive cortical calcification has been associated with JAM2 mutations." (PMID 36862146, 2023). "Central pontine calcifications are highly suggestive of MYORG mutations that also cause a significant degree of cerebellar atrophy and seem to generate a more severe phenotype." (PMID 36862146, 2023). "Compared with other pathogenic genes, brainstem calcifications affecting the pons and cerebellar atrophy could be the prominent features in MYORG mutation carriers." (PMID 34745211, 2021).
Cognitive impairment (2 papers, 2024 to 2025). Abnormal cognition is characterized by deficits in thinking, reasoning, or remembering. "SLC20A2 and MYORG variants had higher detection rates, with cognitive impairment and psychiatric symptoms being common in PFBC patients." (PMID 40456615, 2025). "This integrative analysis identifies SLC20A2 and MYORG as predominant genetic contributors to PFBC, with distinct neuropsychiatric manifestations (cognitive deficits, psychiatric symptoms) representing hallmark clinical features." (PMID 40456615, 2025).
Limb dystonia (1 paper, 2020). Focal limb dystonia is a form of focal dystonia (see this term), characterized by dystonic spasms of arm or leg muscles accompanied by repetitive, twisting movements or abnormal positions or postures. "One associated extrapyramidal sign in MYORG-related disease was limb dystonia." (PMID 32211515, 2020).
migraine (1 paper, 2023). "Our case highlights the pathogenic profile of the MYORG gene, and demonstrates the need for exclusion of calcium deposits in the brain for migraine patients with AR inheritance." (PMID 36816548, 2023).
pseudohypoparathyroidism (1 paper, 2024). "Despite the thorough analysis, no known pathogenic variants were found in genes typically associated with Fahr’s syndrome (e.g., XRP1, PDGFRB, JAM2, PDGFB, SLC20A2, or MYORG) or pseudohypoparathyroidism (e.g., GNAS, STX16, or GNASAS1)." (PMID 39519162, 2024).
mitochondrial disease (1 paper, 2025). "Eight patients had IBGC (variants in SLC20A2, PDGFB, MYORG), 4 had mitochondrial disease (MT-TL1), and 2 had monogenic vascular conditions (GAL, MAP3K6)." (PMID 40947452, 2025).
movement disorder (1 paper, 2022). Neurological conditions resulting in abnormal voluntary or involuntary movement, which may impact the speed, fluency, quality and ease of movement. "In contrast, myogenesis regulating glycosidase (MYORG) is a glycosidase that has an important role in myoblast differentiation and is involved in movement disorders and cognitive impairment." (PMID 35217678, 2022).
MYORG also shares sentences with these, for which no sentence is quoted: dementia (2 papers); abortion (1); Dystonia (1); Fabry disease (1); memory impairment (1); multiple myeloma (1); neurological disorder (1); Stroke (1); Vertigo (1).